ABCB1 (ATP binding cassette subfamily B member 1)
Diseases named in the same sentence as ABCB1 in open-access papers (continued):
Sharing a sentence is not in itself a finding about the gene and the disease.
osteosarcoma (continued). "A study evaluated the effect of ABCB1 silencing, and verapamil and CBT1 (an ABC transporter inhibitor) showed similar activities under both conditions, with the gene-silenced condition being slightly more effective in overcoming drug resistance in osteosarcoma." (PMID 34208283, 2021). "It was found that pre-treatment osteosarcoma biopsy samples with positive ERCC1 immunohistochemistry had worse prognosis both with regard to event free and overall survivals, and that those being positive for both ERCC1 and ABCB1 had significantly worse prognosis." (PMID 32961800, 2020). "Furthermore, ERRα was found to increase transcription of ABCB1, and XCT-790 decreased mRNA stability of ABCB1, suggesting that targeting ERRα could have potential in restoring chemotherapy resistance in osteosarcoma." (PMID 32961800, 2020). "HIF-1α has been reported to have a direct linkage with the ABCB1-mediated chemoresistance in osteosarcoma: indeed, HIF-1α is induced during the acquisition of doxorubicin resistance by the continuous exposure to the drug and in turn, it mediates the resistance to doxorubicin by up-regulating ABCB1." (PMID 32155954, 2020). "It has been previously demonstrated that multidrug resistance of osteosarcoma U2-OS cells and hepatoma HepG2 cells was mediated by HSF1-dependent expression of the ABCB1 gene, but not by HSPs expression." (PMID 24165036, 2013).
lung carcinoma (102 papers, 1996 to 2025). "Despite the high number of polymorphisms identified in the ABCB1 gene and the fact that the most frequent allelic variants have been studied in various diseases, the impact of particular SNPs on lung cancer development remains tentative." (PMID 36755808, 2023). "A study conducted among 225 Han Chinese patients with lung cancer reported the association of ABCB1 SNPs, rs2032582 and rs1128503 with the analgesic effect and dose of sufentanil taken for pain relief." (PMID 36422103, 2022). "Findings of this study suggest that ABCB1 promoter methylation cannot be considered a potential diagnostic, predictive or prognostic biomarker in lung cancer." (PMID 33066132, 2020). "This study aimed to evaluate the association between the SNP 3435 and the expression of the ABCB1 gene in lung cancer patients in the Polish population in comparison to clinicopathological parameters and treatment." (PMID 32277145, 2020). "In this retrospective study, we investigated ABCB1 polymorphism on response and toxicity in taxane‐based chemotherapy in lung cancer patients." (PMID 31571407, 2019). "In conclusion, the ABCB1 polymorphism G2677T/A and C3435T correlated with high AUC and poor taxane response in lung cancer and predict neurotoxicity of taxane‐based chemotherapy." (PMID 31571407, 2019). "We evaluated the association between ABCB1 polymorphisms and toxicities from all 122 lung cancer patients." (PMID 31571407, 2019). "Non‐small cell lung cancer patients with ABCB1 2677 and 3435 variants had a higher probability of shorter PFS for paclitaxel‐based chemotherapy." (PMID 31571407, 2019). "After correlating the ABCB1 genotyping results with age, gender, smoking, histological type of cancer, tumour stage, and grade status, none of the genetic polymorphisms were found to have any influence on lung cancer phenotype." (PMID 36755808, 2023). "Nevertheless, the presented results provide further evidence that ABCB1 gene polymorphisms and their haplotype might be genetic risk factors and potential biomarkers for lung cancer." (PMID 36755808, 2023). "ABCB1 reduces intracellular concentrations of cytotoxic drugs, and is associated with chemotherapy resistance in bladder cancer and with chemotherapy resistance and shorter survival in lung cancer." (PMID 35406487, 2022). "In this study, we evaluated the frequency of ABCB1 polymorphisms in lung cancer patients and studied whether the ABCB1 polymorphisms were associated with clinical outcomes or toxicity of taxane‐based chemotherapy." (PMID 31571407, 2019). "The presented study tests the hypothesis that variations (T-129C, C1236T, G2677T/A, and C3435T) in the ABCB1 gene, which forms a biological barrier against toxins/xenobiotics, may influence the risk of lung cancer and may be a prognostic marker in patients with non-small cell lung cancer (NSCLC)." (PMID 36755808, 2023). "Telmisartan (7a)significantly inhibited the SP phenotype of ABCG2+ MCF-7 breast cancerand ABCC1+ A549 lung cancer cells, but only modestly affected ABCB1+A2780 V SP and IGROV-1 SP ovarian and PC3-DR and DU145-DR prostatecancer cells." (PMID 39693499, 2025). "Our results demonstrate that chelating drug-induced labile Zn2+ by nanosized TPEN at low dose enhances lung cancer chemotherapy by inhibiting ABCB1, providing a feasible strategy to overcome chemoresistance in lung cancer." (PMID 39507258, 2024). "In summary, nanosized TPEN at low dose endows DOX with the killing ability on lung cancer cells that are insensitive to chemotherapy through inhibiting ABCB1." (PMID 39507258, 2024). "Our findings reveal that DOX induces the increase of labile Zn2+ in lung cancer cells that contributes to tumor cells’ resistance to chemotherapy through potentiating ABCB1-mediated drug export." (PMID 39507258, 2024).
lung carcinoma (continued). "Taken together, our results demonstrate that chelating drug-induced labile Zn2+ by nanosized TPEN at low dose enhances lung cancer chemotherapy by inhibiting ABCB1, providing a feasible strategy to overcome chemoresistance in lung cancer." (PMID 39507258, 2024). "In these studies, the ABCB1 downstream promoter was hypermethylated also, and demethylation both decreased ABCB1 RNA expression in the lung and esophageal lines, and re-sensitized cells to cisplatin in the case of the lung cancer line, A549." (PMID 37686513, 2023). "Here, we show ZIP1+ CAF subset is enriched in lung cancer models after chemotherapy and actively transfers Zn2+ to cancer cells, promoting ABCB1-mediated chemoresistance." (PMID 36207295, 2022). "Here the authors show that a zinc-transporter positive CAF subset is enriched in lung cancer models after chemotherapy and actively transfers zinc to cancer cells, promoting ABCB1-mediated chemo-resistance." (PMID 36207295, 2022). "An altered methylation pattern was detected in the promoters of ABCB1, ABCC1, and ABCG2 in breast and lung cancer, whereas the defective activity of histone acetylases including EP300, CBP, and PCAF was reported to be implicated in ABCB1 overexpression." (PMID 35205642, 2022). "ZIP1+ fibroblasts can act as Zn2+ reservoirs to absorb Zn2+ and transfer it to cancer cells through gap junctions, thereby leading to ABCB1-mediated drug extrusion in lung cancer cells." (PMID 36207295, 2022). "We found that expression of ZIP1 in the tumour stroma, specifically in fibroblasts, was associated with chemotherapy resistance in lung adenocarcinoma, and correlated with ABCB1 expression in the tumour cells of lung cancer patients." (PMID 36207295, 2022). "In paclitaxel resistant lung cancer cells the combination counteracted the resistance to mitotic catastrophe through downregulation of MDR1/ABCB1 protein." (PMID 35719948, 2022). "In this study, for the first time, ABCB1 expression and P-gp activity on Dox-resistant A549 lung cancer cell line were investigated in the presence of amphiphilic-cationic CPPs and their nano-complexes." (PMID 33995950, 2021). "ABCB1 reportedly plays an important role in overcoming ABCB1-mediated docetaxel resistance in lung cancer." (PMID 32503508, 2020). "The presented data suggests an important role of ABCB1 in lung cancer which we would like to prove in our future research." (PMID 32277145, 2020). "The present study is the first to analyze the influence of SNPs at rs2032582, rs1045642 and rs1128503 loci in ABCB1 gene on the sufentanil consumption and analgesic effect in patients who underwent radical resection of lung cancer." (PMID 30455395, 2019). "Here we demonstrate for the first time that CHD1L can contribute to cisplatin resistance by upregulating the ATP-Binding Cassette Sub-Family B Member (ABCB1) gene in lung cancer cells." (PMID 30718500, 2019). "This was consistentto the observations in paclitaxel resistant lung cancer cell line,wherein ABCB1 gene expression increased upto 1000-fold, while acopy number gain of only 12 was found in the ABCB1 genomicregion." (PMID 31223218, 2018). "Second, we identified amplification of the ABCB1 gene and subsequent overexpression of the drug efflux pump MDR1 as the cause of acquired PU-H71 resistance in A549 lung cancer cells and SW480 colon cancer cells." (PMID 28032595, 2017). "Our results are in accordance with a previous study pointing to differences in the ABCB1 promoter methylation status between various lung cancer cell lines." (PMID 27689338, 2016). "We recently reported that natural compound including flavonoids, such as resveratrol inhibits MDR transport function directly in ABCB1 overexpressing NCI-H460 lung cancer cells." (PMID 27304668, 2016). "Combination approaches with ETAR antagonists or switching to non-ABCB1 substrate FGFR inhibitors represent innovative strategies to manage nintedanib resistance in lung cancer." (PMID 27367030, 2016).
lung carcinoma (continued). "In another ABCB1-overexpressing non-small cell human lung cancer cell line A549/T (PTX-resistance) and its parental cells A549, we observed similar reversal effects of nobiletin to PTX and other chemotherapeutic agents." (PMID 26689156, 2015). "Researchers have discovered that common polymorphisms of ABCB1 and ABCC1 can influence metabolism and disposition of the well-established carcinogen, NNK, and potentially increase the lung cancer risk." (PMID 23762359, 2013). "The ABCB1 gene (translated as the P-glycoprotein), part of the ATP-binding cassette transporter family, has been correlated with poor prognosis and cancer recurrence in lung cancer." (PMID 39457585, 2024). "Moreover, a connection between ERBB signaling and ABCB1 expression has been described in ovarian and lung cancer models: Afatinib decreased ABCB1 expression in ABCB1‐overexpressing cells by inhibiting the activation of PI3K/AKT signaling and NF‐κB activation." (PMID 36181342, 2023). "Additionally, ABCB1 gene expression is reduced in lung cancer tissue taken during surgery compared to normal cells." (PMID 36755808, 2023). "Furthermore, ZIP1+ fibroblasts act as Zn2+ reservoirs to absorb and transfer Zn2+ to lung cancer cells, inducing ABCB1-mediated drug extrusion." (PMID 36207295, 2022). "Furthermore, it has been shown that also flavokawain A downregulated p-glycoprotein (MDR1/ABCB1) expression via inhibition of the PI3K/Akt signaling pathway in paclitaxel (PTX)-resistant lung cancer cells in a dose- and time-dependent manner." (PMID 34073042, 2021). "In the current study, different sequences of cell-penetrating peptides (CPPs) containing tryptophan, lysine, and arginine and their nano-complexes were synthesized and their impact on the expression and activity of the ABCB1 gene was evaluated in the A549 lung carcinoma cell line." (PMID 33995950, 2021). "Thus, combination treatment with volasertib and P22077 showed a strong synergism in paclitaxel-resistant lung cancer by down-regulation of MDR/ABCB1." (PMID 33207738, 2020). "Our study is the first to evaluate the correlation between SNPs at the rs1799971, rs563649 and rs1323040 loci in the OPRM1 gene and the rs2032582, rs1045642 and rs1128503 loci in the ABCB1 gene with sufentanil consumption in Chinese Han patients who underwent radical resection of lung cancer." (PMID 30455395, 2019). "For the first time, our study evaluated the correlation between SNPs at the rs1799971, rs563649 and rs1323040 loci in OPRM1 and the rs2032582, rs1045642 and rs1128503 loci in ABCB1 with sufentanil consumption in Chinese Han patients who underwent radical resection of lung cancer." (PMID 30455395, 2019). "Therefore, the purpose of this study was to evaluate the association of ABCB1 polymorphisms, adverse event, PFS and pharmacokinetic parameters in Chinese lung cancer patients treated with taxane‐based chemotherapy." (PMID 31571407, 2019). "In vitro and in vivo studies show that cisplatin enriches a subpopulation of NOTCH-regulated CD133-expressing stem-like lung cancer cells that cause cross-resistance to paclitaxel and doxorubicin by upregulation of ABC drug transporters: ABCG2 and ABCB1 (also called MDR-1 or P-glycoprotein)." (PMID 30087852, 2018). "In lung cancer, ABCB1 expression is initially low, but this may change after exposure to chemotherapy as part of acquired drug resistance." (PMID 27988838, 2017). "Moreover, combination approaches with ETAR antagonists or a switch to non-ABCB1 substrate FGFR inhibitors represent innovative strategies to manage nintedanib resistance in lung cancer." (PMID 27367030, 2016). "Moreover, in lung cancer cells, gal-3 silencing increased drug sensitivity to cisplatin and paclitaxel by regulating the ABCB1 and ABCG2 transporter pumps through β-catenin." (PMID 27835877, 2016).
lung carcinoma (continued). "Concerning the clinics, the fact that nintedanib is an ABCB1 substrate might impair its efficacy as a single treatment not only in lung cancer, but also in other cancer types." (PMID 27367030, 2016). "Compared with the wild A/A genotype, ABCB1 rs3842 A/G or G/G (OR 1.36, 95% CI 1.06–1.76) and ABCC1 rs212090 A/T or T/T (OR 1.37, 95% CI 1.03–1.83) genotypes were associated with an increased risk of lung cancer." (PMID 24212786, 2011). "Hence, examining the acetylation status of the −981 to −817 region of the ABCB1 promoter seemed interesting in the H69 lung carcinoma cell lines." (PMID 17667922, 2007). "In this study, we evaluated the potential of the ALA-hemin combination in enhancing the therapeutic effects of ALA-PDT against human lung cancer by regulating ABCG2 and ABCB1 expressions with hemin." (PMID 39584916, 2024). "Specifically, the elevated levels of ABCB1 compromise the efficacy of drugs, such as DOX, EGFR tyrosine kinase inhibitors, and cisplatin in lung cancer." (PMID 39507258, 2024). "Meanwhile, we found a similar decrease of drug-resistant genes (ABCB1, ABCC1, and ABCG2) in lung cancer spheroids after apatinib treatment, which was further confirmed in CDDP-resistant A549 cells." (PMID 33980809, 2021). "In summary, three studies have investigated ABCB1 and three studies ABCG2 promoter methylation in lung cancer." (PMID 33066132, 2020). "Findings for MDR cell line models suggest that changes in ABCB1 and ABCG2 promoter methylation are involved in acquiring MDR in lung cancer." (PMID 33066132, 2020). "We thus verified the correlation between ABCB1 expression and NF-κB signaling activation in CHD1L overexpressed lung cancer cell lines." (PMID 30718500, 2019). "In some lung cancer specimens, other ABC transporters, such as ABCB1 and ABCG2, were detected in low quantities." (PMID 27649127, 2016). "Our previous observations on lung cancer cells NCI-H460 overexpressing ABC transporter proteins (LRP, ABCB1, BCRP, ABCC1 ABCC2 and ABCC3) confirmed the ability of resveratrol lignans to overcome the resistance to PTX." (PMID 27304668, 2016). "To further elucidate the relationship between the major drug transporters and the resistance to paclitaxel, we measured the expression of ABCB1 and ABCC1 in lung cancer cell lines by quantitative real-time RT-PCR." (PMID 22179563, 2012). "Our results indicate that the drugs induce the increase of labile Zn2+ in lung cancer cells, leading to an increase in AKT phosphorylation to upregulate ABCB1 at protein expression level, and to ATP production that enables ABCB1 to obtain more energy at the metabolic level." (PMID 39507258, 2024). "We analyzed the potential involvement of hemin combination to improve the efficacy of ALA-PDT to induce cell death in A549 lung cancer and hypothesized that it regulates the PpIX accumulation by repressing the ABCG2 and ABCB1 expression." (PMID 39584916, 2024). "The multidrug resistance-associated protein 1 (MRP1), known as ABCC1, was first recognized in lung cancer cells that had no expression of ABCB1 (MDR1 or P-gp)." (PMID 32380783, 2020). "MALAT1-mediated upregulation of STAT3 also correlates with its reported role in enhancing the expression of MRP1 (ATP binding cassette subfamily C member 1) and MDR1 (ATP binding cassette subfamily B member 1) through STAT3 activation, in turn driving cisplatin-resistance in lung cancer." (PMID 29702599, 2018). "Among these, multidrug resistance-associated protein 1 (MRP1), also known as ABCC1, was first identified from drug-resistant lung cancer cells that did not express ABCB1 (MDR1 or P-glycoprotein)." (PMID 30486290, 2018). "With respect to targeted small molecule inhibitors, no connection between lung cancer subtypes and ABCB1 induction has been described." (PMID 27367030, 2016).
lung carcinoma (continued). "Interestingly, it was reported that treatment with doxorubicin induced a large increase in ABCB1 expression in lung cancer cells, whereas no significant change in expression was observed in normal lung cells." (PMID 36674503, 2023). "For example, subfamily B member 1 (ABCB1), also known as MDR-1 or p-glycoprotein (P-gp), was first identified and cloned, and was subsequently shown to be responsible for clinical MDR in many cancers, such as colorectal cancer, breast cancer, lung cancer, etc.." (PMID 34959397, 2021). "Thus, paclitaxel-resistant lung cancers are more sensitive to gefitinib and readily undergo apoptotic cell death compared with non-resistant lung cancer, through downregulation of ABCB1, ABCC9, ABCG2, PLK1, and EGFR." (PMID 34503223, 2021). "However, upregulation of ABCB1 expression in lung cancer does not appear to be exclusive for SCLC, as it has also been observed in NSCLC following chemotherapy." (PMID 27367030, 2016). "Thus, the role of ABCB1 and ABCG2 methylation in lung cancer remains unclear to date." (PMID 33066132, 2020). "ABCC1, commonly referred to as multidrug resistance protein 1 or MRP1, is a phosphorylated glycoprotein first identified in a MDR lung cancer lacking ABCB1." (PMID 37438132, 2023). "ABCB1 expression has been shown in many cancer types; however, ABCB1 modulation therapy has not been effective against tumours that possess ABCC family-mediated drug resistance, as shown for the doxorubicin-selected lung cancer cell line H69AR and HL60/AR." (PMID 29401721, 2018).